BECN1 (beclin 1)
Diseases named in the same sentence as BECN1 in open-access papers (continued):
Sharing a sentence is not in itself a finding about the gene and the disease.
breast carcinoma (continued). "Interestingly, high expression of adiponectin, adiponectin receptor 2 (ADIPOR2), and beclin 1 (BECN1, the protein implicated in the autophagic programmed cell death), significantly correlated with increased overall survival in chemotherapy-treated breast cancer patients." (PMID 36555323, 2022). "Therefore, Beclin-1 could not only reduce the risk of breast cancer, but also affected the development of breast cancer by regulating autophagy." (PMID 35414025, 2022). "Therefore, in addition to the monoallelic loss of BECN1 in breast cancer, miR-20a-mediated downregulation of autophagy pathway might be another mechanism that promotes malignant transformation." (PMID 28628113, 2017). "Monoallelic deletion of the BECN‐1 gene, which encodes Beclin‐1 protein, is common in HER2+ breast cancer." (PMID 41329030, 2025). "Dihydroartemisinin (DHA)‐loaded liposomes enhanced the circulation time of Epirubicin and improved its efficacy in different breast cancer cells by reducing Bcl‐2 activity, promoting Beclin‐1 release, and activating Bax." (PMID 40529859, 2025). "On the other hand, the deletion of autophagy-related genes has been shown to promote tumor formation, such as the deletion of ATG7 in liver tumors and the deletion of Beclin-1 in breast cancer." (PMID 40917720, 2025). "This innovative strategy enabled the identification of genes involved in Beclin 1-mediated growth suppression, advancing our knowledge of this pathway in breast cancer." (PMID 40650785, 2025). "In turn, in the case of HER2-positive breast cancer, selenium inhibits growth of trastuzumab-resistant human breast cancer cells via downregulation of Akt and beclin-1." (PMID 40075686, 2025). "They found that CDH1 and CTNNA1 were required for Beclin 1 to inhibit breast cancer cell growth by conducting a CRISPR screen in cells with and without Beclin 1 expression." (PMID 40650785, 2025). "This has been demonstrated by preventing tumor formation in a genetically modified mouse model with higher basal autophagy levels and by decreasing tumor growth in HER2+ breast cancer xenografts treated with Tat-BECN1, an autophagy-inducing peptide." (PMID 40754831, 2025). "In early‐stage breast cancer, hypermethylation of BECN1, LC3B, and ATG5 suppresses autophagic activity, contributing to tumorigenesis." (PMID 41329030, 2025). "DHA‐EPI liposomes induced excessive autophagy in breast cancer cells by reducing Bcl‐2, enhancing Beclin‐1 release, and activating Bax." (PMID 40529859, 2025). "In breast cancer, hypermethylation of BECN1, LC3B, and ATG5 is frequently observed in early‐stage tumors, resulting in reduced autophagic activity, accumulation of damaged organelles, genomic instability, and tumor initiation." (PMID 41329030, 2025). "The initial indication of autophagy’s involvement in cancer came from the identification of Beclin 1 as a potential tumor suppressor in breast cancer." (PMID 40723786, 2025). "As a result of Beclin-1 gene overexpression in breast cancer, MCF7 cells have been shown to increase autophagic activity; thereby, cell growth and tumor formation are reduced using in vivo breast cancer models." (PMID 39858015, 2025). "Homozygous-BECN1-deficient mice exhibit embryonic lethality, while heterozygous disruption of BECN1 leads to the occurrence of lung cancer, liver cancer, lymphoma and mammary tumor." (PMID 40659605, 2025). "In various cancers such as breast cancer, ovarian cancer, and colorectal cancer, the expression level of BECN1 is significantly reduced, which is positively correlated with poor prognosis for patients." (PMID 39048965, 2024). "The overexpression of the Beclin-1 gene in breast cancer MCF-7 cells has been found to enhance autophagic activity, subsequently inhibiting cell proliferation and tumor formation in nude mice." (PMID 38315272, 2024). "This derivative caused a decrease in concentrations of Beclin-1 and LC3B and inhibited autophagy in both analyzed breast carcinoma cells." (PMID 39199694, 2024).
breast carcinoma (continued). "In our study, we have proved that compound 3b increases the number of cells with active beclin-1 in dose-dependent manner in both breast cancer cells." (PMID 38700244, 2024). "To understand docetaxel resistance in MDA-MB-231-pLKO/miR-622 cells by inhibiting miR-30a, we evaluated the impact of anti-miR-30a treatment on beclin 1-mediated autophagy signaling in breast cancer cells transfected with pLKO/miR-622." (PMID 38339408, 2024). "Out of 17 cases used for BECN1 mRNA T/N ratio, 9 had positive nodal metastasis, while 14 cases had luminal type breast cancer and 3 had triple negative type." (PMID 38787424, 2024). "Our research showed that compound 3b slightly induced the level of beclin 1 in both breast cancer cell lines." (PMID 38700244, 2024). "GRB2 co-immunoprecipitated with BECN1 in several breast cancer cell lines and regulates autophagy through a mechanism involving the modulation of the class III PI3Kinase VPS34 activity." (PMID 38182563, 2024). "BECN1 haploinsufficiency is considered one of tumorigenesis pathways in breast cancer (Vega-Rubín-de-Celis 2019), thus it is expected to be expressed at lower levels in tumor tissues than in normal ones." (PMID 38787424, 2024). "An analysis of breast cancer tissues has shown that approximately 70% of specimens exhibit reduced protein expression levels of Beclin-1." (PMID 38315272, 2024). "Crocetin demonstrated beneficial effects in breast cancer cells (MCF-7) by regulating the autophagy markers (reduced Beclin-1 level)." (PMID 38645503, 2024). "Here, we generated adipocyte-specific Becn1 KO conditions during breast cancer development by crossing MMTV-PyMT mice with BaKO mice (PyBaKO)." (PMID 38744820, 2024). "Clinical data suggests that BECN1 has tumor-suppressive functions, as monoallelic BECN1 deletion has been found in approximately 30% of breast cancer and 77% of patients with ovarian cancer." (PMID 38744820, 2024). "Examination of primary mammary tumor samples and breast cancer cell lines showed a high occurrence of eliminating one copy of the BECN1 gene." (PMID 39436197, 2024). "Suppression of BCL2 can upregulate the expression of beclin‐1, thus leading to apoptosis in breast cancer cells." (PMID 37484971, 2023). "BECN1 has been generally identified as a tumor-suppressing gene in the last decades because decreased BECN1 expression level is widely observed in various types of cancer, including breast cancer, glioblastoma multiforme, and ovarian and prostate cancer." (PMID 37108476, 2023). "The association between autophagy and cancer was initially established in 1999 with the discovery that Beclin 1, encoded by the BECN1 gene, facilitates autophagy in human MCF‐7 breast cancer cells and inhibits tumour cell proliferation." (PMID 37837401, 2023). "Human BECN1 monoallelic deletions are reported in up to 50% of breast cancers and 75% of ovarian cancers." (PMID 37213283, 2023). "The expression of BECN1 in breast cancer tissues has been found to be negatively correlated with that of BCL‐2." (PMID 36852470, 2023). "A previous study also indicated that autophagy stimulation by Beclin-1-loaded polymeric NPs significantly diminishes breast cancer progression." (PMID 36593951, 2023). "Beclin 1 has close relationship to TNBC as bioinformatic analysis has revealed that low mRNA level of Beclin 1 is more commonly detected in TNBC than in other breast cancer subtypes." (PMID 37598181, 2023). "Crocetin was effective in breast cancer cells (MCF-7) through regulation of the autophagy pathway (decreased the level of beclin-1)." (PMID 36742140, 2023). "CRISPR/Cas9 knockdown of CTNNA1 and CDH1 reverses the inhibitory effect of Beclin-1 on breast cancer cell proliferation." (PMID 36741258, 2023). "The decrease in BECN1 degradation induced by SLC9A3R1 resulted in enhanced autophagy stimulating activity of breast cancer cells." (PMID 36980514, 2023).
breast carcinoma (continued). "The inhibiting long intergenic non-protein coding RNA, regulator of reprogramming (linc-ROR) can induce autophagy by increasing Beclin-1 expression and inducing gemcitabine and tamoxifen resistance in breast cancer." (PMID 36899946, 2023). "Beclin 1 is also a haploinsufficient tumor suppressor and mono-allelically deleted in 40–75% of human sporadic breast cancer and ovarian cancer." (PMID 36765914, 2023). "BECN1 is found mono-allelically deleted in about 40% to 75% of human sporadic breast cancers and ovarian cancers." (PMID 36008963, 2022). "Beclin-1 is deleted in more of 50–70% of sporadic human breast cancers, underscoring the involvement of autophagy in breast cancer." (PMID 35884904, 2022). "For example, the knockdown of BECN1 significantly enhanced breast cancer cell sensitivity to paclitaxel through caspase-dependent apoptosis." (PMID 35012553, 2022). "Beclin-1, as an important tumor suppressor gene, was missing in most breast cancer patients, especially in TNBC." (PMID 35414025, 2022). "For example, autophagy-related gene Beclin 1 decreases in breast cancer, and its downregulation will promote epithelial mesenchymal transition and reduce the inhibitory effect on EGFR, thus promoting the growth and migration of breast cancer." (PMID 35692501, 2022). "In prostate and breast cancer, the expression of several essential autophagy genes was found to be partially downregulated, such as Beclin-1 (BECN1) 37,38." (PMID 36313039, 2022). "The deletion of BECN1 in breast cancer cells and the deletion of ATG13 or ULK1 in glioblastoma cells led to similar results." (PMID 36197606, 2022). "Studies have shown that Beclin-1 gene deletion is present to varying degrees in 75% of ovarian cancers, 50% of breast cancers, and 40% of prostate cancers." (PMID 36104717, 2022). "It has been established that Beclin 1 upregulation reduces estrogenic signaling and thus impairs the growth response of ER+ breast cancer cells." (PMID 36077830, 2022). "Carnosol induced both beclin-1 independent autophagic and apoptotic cell death of breast cancer cells." (PMID 35712465, 2022). "Similar to what has been observed with other ERBB family members, HER2 has also been reported to interact with Beclin-1 in breast cancer cells." (PMID 35309939, 2022). "For example, in ER (estrogen receptor)-positive breast cancer cells, suppressing beclin-1 boosted tamoxifen sensitivity in vitro, and lower beclin-1 expression predicts a better prognosis in patients with ER-positive breast cancer." (PMID 35326612, 2022). "In breast cancer, Beclin-1 cooperates with a member of PI3KC3 complex, UVRAG, to recruit E-cadherin and other components of the E-cadherin/catenin complex to the membrane of breast cancer cells." (PMID 35884904, 2022). "In mukonal-treated breast cancer cells, there was an increase in the expression level of autophagy proteins, Beclin-1, LC3-I, and LC3-II, thus leading to autophagic cell death." (PMID 36104717, 2022). "Exosomes derived from breast cancer cells can activate autophagy-related genes, including LC3 and Beclin-1, to promote the proliferation, motility, and invasion of breast cancer cells." (PMID 35571530, 2022). "The novel compound (Les-3331) tested in that study inhibited LC3A, LC3B, and Beclin-1 concentrations in both analyzed breast cancer cells." (PMID 35456915, 2022). "While Beclin-1, as a key gene for the formation of autophagosome initiation complex, was highly expressed in breast cancer, the proliferation and drug resistance of TNBC were dramatically restrained." (PMID 35414025, 2022).
breast carcinoma (continued). "Rottlerin treatment results in BCL2- and BECN1-independent autophagic death in apoptosis-resistant breast cancer MCF-7 cells." (PMID 36497321, 2022). "Beclin-1 acts as a tumor suppressor in mammals, and decreased Beclin-1 protein compared to normal tissue was found in breast cancer, colon cancer, cholangiocarcinoma, ovarian cancer, renal cell carcinoma, non-small cell lung cancer, and gastric cancer." (PMID 35806184, 2022). "Our preliminary data demonstrate a potential prognostic value of TFEB, SIRT1, and Beclin-1, likely for their role within autophagy regulation in patients affected by breast cancer and treated with anti-blastic therapy." (PMID 34663249, 2021). "There are several conflicting studies that report the correlation between Beclin-1 expression and breast cancer prognosis." (PMID 34490076, 2021). "In the present study, selenium enhanced the antitumor effect of Tz on Tz-resistant breast cancer cells via inhibition of beclin-1-related autophagic activity." (PMID 34525121, 2021). "• TFEB, SIRT1, and Beclin-1 seem to have a potential prognostic significance in patients with chemo-treated breast cancer." (PMID 34663249, 2021). "Pull-down experiments suggested a molecular interaction between Bag-1 and Beclin 1 in breast cancer cell lines." (PMID 33561998, 2021). "Our data suggested that Bag-1 indirectly forms a complex with Beclin 1 through at least one bridging molecule and improves autophagy and cell survival during starvation in breast cancer cell lines." (PMID 33561998, 2021). "Further, Beclin-1, another autophagy mediator, was stained in breast cancer cells, but few cytoplasmic positive vesicles were detected and only occasional staining in cGAS positive MN." (PMID 34123836, 2021). "The present study found that selenium induced beclin-1-related autophagy in Tz-sensitive breast cancer cells after treatment with selenium combined with Tz." (PMID 34525121, 2021). "The mutation of the BECN1 and ATG7 genes observed in human ALDH+ breast cancers resulted in reduced proliferation of cancer stem cells (CSCs) and loss of their ability to self-renew." (PMID 33804163, 2021). "Of note, most of the tumor-suppressive effects of autophagy in breast cancer have been attributed to Beclin1, and BECN1 is frequently monoallelically deleted in human breast cancer cells." (PMID 34207792, 2021). "BECN1 silencing enhanced the sensitivity of breast cancer cells to tamoxifen by reducing tumor cell proliferation, migration, and invasion capabilities." (PMID 33718194, 2021). "To investigate probable Bag-1/Beclin 1 interaction, we first performed His6-pull down experiments reciprocally in three different breast cancer cell lines, ranging from triple negative to triple positive." (PMID 33561998, 2021). "It has been shown that 40-75% of sporadic human breast cancers in the Beclin-1 gene region have mono-allelic deletion." (PMID 33507706, 2021). "Tissue microarrays of 76 patients with breast cancer were stained with six IHC markers (MnSOD, Beclin-1, LC3, BNIP3, Parkin, and cleaved caspase 3)." (PMID 34490076, 2021). "TFEB, SIRT1, and Beclin-1 seem to have a potential prognostic significance in patients with chemo-treated breast cancer, likely because of their role in the regulation of autophagy." (PMID 34663249, 2021). "Combination of Tz and selenium inhibited beclin-1-related autophagy in Tz-resistant breast cancer cells." (PMID 34525121, 2021). "Inhibiting autophagy by silencing BECN1 reduced the degradation of the intracellular domain of Notch1, leading to an increased migration of breast cancer cells." (PMID 34207792, 2021). "Using GEPIA 2.0 and bc-GenExMiner 4.5 to analyze TCGA databases, we found that the mRNA expression of the autophagy-related markers LC3B and Beclin-1 was positively correlated with E-cadherin expression in all breast cancer and TNBC patients." (PMID 34481526, 2021).
breast carcinoma (continued). "Deletion of BECN1 gene occurs in 40% cases of prostate cancer, 50% cases of breast cancer and 75% cases of ovarian cancer." (PMID 33804163, 2021). "We used MCF-7 human breast carcinoma cells as a research model because of the low amounts of endogenous BECN1 observed in these cells compared to other cell lines." (PMID 34131122, 2021). "Among the top hits, the PGR (progesterone receptor), GREB1 (growth regulation by estrogen in breast cancer 1), and BECN1 mRNAs were validated." (PMID 33542201, 2021). "This suggests that BECN1 is dispensable for PARPi-mediated autophagy activation in MCF-7 breast cancer cells." (PMID 33473172, 2021). "In fact, some authors have found that in breast cancer the increase in autophagy induces the interaction between Beclin-1 and HER2 with consequent tumorigenesis." (PMID 34769649, 2021). "Such a phenomenon was observed in MCF7 breast cancer cells treated with okadaic acid, which inhibits the phosphatase PP2A implicated in Beclin-1 dephosphorylation." (PMID 34943939, 2021). "In breast cancer, the inhibition of the autophagy-related proteins Beclin-1, ATG12, and LC3 reduces the stemness-like phenotype, reinforcing that the activation of protective autophagy supports the maintenance of the breast CSC population." (PMID 33194736, 2020). "To further validate autophagic induction in breast cancer cells, we measured the protein levels of Beclin-1, Atg3, and the conversion of LC3-I to LC3-II which are the hallmarks of autophagy induction." (PMID 33013353, 2020). "Some studies suggested an association between Beclin 1 and HER2 in breast cancer, and a correlation between HER2 amplification in breast cancer with BECN1 DNA copy loss was found." (PMID 33287140, 2020). "In human breast cancer cells, DHEA and EPEA induced Bcl-2 phosphorylation at serine 70 reducing its physical association with Beclin-1 and leading to increased levels of Beclin-1 unbound protein, thus resulting in autophagosome formation." (PMID 32224850, 2020). "Re-expression of BECN1 in a heterozygous deleted BECN1 human breast cancer cell line MCF7 reduced clonogenicity in soft agar." (PMID 31923184, 2020). "Conversely, the activation of ER stress triggered both apoptosis and autophagy through the IRE1/JNK/beclin-1 axis in breast cancer cells." (PMID 31996710, 2020). "On the other hand, HER2 binds the Beclin-1 and suppresses the autophagy, and then induces the tumorigenesis of breast cancer cells." (PMID 33375363, 2020). "As a result, inhibition of autophagic genes including LC3 and Beclin-1 inhibits proliferation, movement, invasion, and increases apoptosis rate of breast cancer cells." (PMID 32426106, 2020). "In transplantation assays, depletion of Beclin 1 in breast cancer stem cells inhibited xenograft tumor formation in immunodeficient mice." (PMID 32195258, 2020). "When comparing breast cancer stem cell-enriched mammospheres to heterogenous cultures of adherent breast cancer cells, one study found that autophagic flux and Beclin 1 expression are higher in mammospheres." (PMID 32195258, 2020). "In breast cancer, evidence shows that proteins involved in autophagy, such as beclin-1, regulate cell growth and interfere in estrogen signaling." (PMID 32321078, 2020). "To further demonstrate the effect of eEF-2K suppression on the sensitivity of mTOR inhibitor against breast cancer cell, we compared the cell viability in response to combined treatment of mTOR inhibitor with eEF-2K siRNA or Beclin 1 siRNA." (PMID 33144562, 2020). "Mukonal induced autophagic cells death in breast cancer cells as was evidenced by formation of autophagosomes and enhanced expressions of Beclin-1, LC3B-I and LC3B-II proteins." (PMID 32809085, 2020). "As a result, inhibition of autophagic genes including LC3 and Beclin-1 inhibits the proliferation, movement, invasion, and increases the apoptosis in breast cancer cells." (PMID 32426106, 2020).